PROCR (protein C receptor)
Description:
Binds activated protein C. Enhances protein C activation by the thrombin-thrombomodulin complex; plays a role in the protein C pathway controlling blood coagulation.
Synonyms: CD201; EPCR; CCD41; CCCA
Tractability: Small molecule: a structure with a bound ligand is known; it has a high-quality binding pocket. Antibody: its Gene Ontology location is reachable by antibodies, with high confidence; UniProt predicts a signal peptide or a membrane-spanning region.
Gene: Protein-coding gene on chromosome 20 (35,171,850 to 35,216,240, forward strand). Ensembl gene ENSG00000101000.
Subcellular location: Membrane
Pathways (Reactome):
Hemostasis: Cell surface interactions at the vascular wall; Regulation of clotting cascade
Gene Ontology:
Molecular function: protein binding; signaling receptor activity
Biological process: negative regulation of coagulation
Cellular component: cell surface; extracellular exosome; focal adhesion; extracellular region; plasma membrane; centrosome; membrane; perinuclear region of cytoplasm
Genetic constraint (gnomAD): Loss-of-function variants: 22 observed, 24.94 expected, observed/expected ratio (o/e) 0.88, 90% interval 0.63 to 1.26. The upper end of that interval is the gene's LOEUF score, 1.26, which puts it in group 5 of 6, group 1 being the genes least tolerant of losing a copy. Missense variants: 288 observed, 319.55 expected, observed/expected ratio (o/e) 0.9, 90% interval 0.82 to 0.99. Synonymous variants: 137 observed, 143.35 expected, observed/expected ratio (o/e) 0.96, 90% interval 0.83 to 1.1.
Homologues: Orthologues: chimpanzee PROCR (99% identical), macaque PROCR (94% identical), rabbit PROCR (78% identical), rat Procr (68% identical), guinea pig PROCR (67% identical), mouse Procr (67% identical), pig PROCR (66% identical), dog PROCR (66% identical).
Diseases named in the same sentence as PROCR in open-access papers:
PROCR is named in the same sentence as 146 diseases in open-access papers, as found by Europe PMC text mining. Sharing a sentence is not in itself a finding about the gene and the disease. The quoted sentences say what the papers report.
malaria (80 papers, 2014 to 2025). Malaria is a serious and sometimes fatal disease caused by a parasite that commonly infects a certain type of mosquito which feeds on humans. "ADNP, but not ADCP, using IEs expressing IT4VAR19 (a PfEMP1 variant that binds to endothelial protein C receptor through a DC8 domain cassette) is higher at hospital presentation in children with uncomplicated malaria than in severe malaria." (PMID 40624161, 2025). "Severe malaria is associated with PfEMP1 binding human endothelial protein C receptor (EPCR) via their CIDRα1 domains." (PMID 39046960, 2024). "PfEMP1s include a subset of variants that binds to endothelial protein C receptor (EPCR) through CIDRα1 domains and whose expression is associated with severe malaria." (PMID 37791774, 2023). "Both approaches showed in concordance that severe malaria was associated with PfEMP1 containing the endothelial protein C receptor (EPCR)-binding CIDRα1 domain, whereas CD36-binding PfEMP1 was linked to non-severe malaria outcomes." (PMID 33908865, 2021). "Plasmodium falciparum parasites causing severe malaria have a stronger affinity for endothelial protein C receptor (EPCR) than parasites from children with uncomplicated malaria." (PMID 30249265, 2018). "More recently, binding of the N-terminal cysteine-rich inter domain region (CIDRα1) of PfEMP-1 to Endothelial Protein-C Receptor (EPCR) has been associated with severe malaria." (PMID 28249043, 2017). "Recent studies have implicated novel receptors, such as endothelial protein C receptor (EPCR) related to severe malaria in Tanzania15, and the receptor gC1qR/HABP1/p32 related to seizures in Mozambique23." (PMID 29066816, 2017). "Parasites binding human endothelial protein C receptor (EPCR) through the CIDRα1 domain of certain PfEMP1 were recently associated with severe malaria in children." (PMID 27354391, 2016). "Sequestration affects the course of clinical malaria; and recent studies have linked the binding of specific PfEMP1s to endothelial protein C receptor (EPCR) with severe malaria pathology." (PMID 25522011, 2014). "Two recent reports have identified the Endothelial Protein C Receptor (EPCR) as a key molecule implicated in severe malaria pathology." (PMID 25541704, 2014). "Severe malaria outcomes are linked to PfEMP1 binding endothelial protein C receptor (EPCR) via their CIDRα1 domains, which are encoded by approximately half of the UPSA var genes and a small subset of UPSB var genes, which likely arose from UPSB/A recombination events." (PMID 40493675, 2025). "Severe malaria is governed in part by the expression of the Plasmodium falciparum Erythrocyte Membrane Protein 1 (PfEMP1) that are encoded by var genes, specifically those variants that bind Endothelial Protein C Receptor (EPCR)." (PMID 34115805, 2021). "Importantly, in contrast to parasites from naïve volunteers, expression of var genes coding for endothelial protein C receptor (EPCR)-binding PfEMP1 that are associated with severe childhood malaria was rarely detected in semi-immune adult African volunteers." (PMID 31295334, 2019). "It was speculated that genetic variation affecting EPCR functionality could influence susceptibility to severe malaria phenotypes, rendering PROCR, the gene encoding EPCR, a promising candidate for an association study." (PMID 25541704, 2014). "In malaria, loss of endothelial protein C receptor links coagulation and inflammation that are induced by parasite sequestration in cerebral malaria, and rs867186-GG is associated with increased sEPCR levels and could mediate protection against severe malaria." (PMID 32153634, 2020). "Plasma levels of Ang2 were associated with markers of malaria severity and levels of var transcripts encoding P. falciparum Erythrocyte Membrane Protein 1 (PfEMP1) containing Cysteine Rich Inter Domain Region α1 (CIDRα1) domains predicted to bind Endothelial Protein C receptor (EPCR)." (PMID 27784899, 2016).
malaria (continued). "Of particular significance for severe outcomes of malaria is the interaction between the CIDRα1-bearing PfEMP1 and the endothelial protein C receptor (EPCR)." (PMID 39046960, 2024). "A subset of PfEMP1 proteins bind to endothelial protein C receptor (EPCR), and their expression correlates with development of the symptoms of severe malaria." (PMID 33408232, 2021). "In malaria, the acute respiratory distress syndrome also presents competitive binding of other surface proteins, such as Endothelial Protein C Receptor (EPCR), that when cleaves its ligand PAR-1, inhibits NFκB activation, reducing overall local inflammation." (PMID 32714336, 2020). "Various studies have implicated PfEMP1 [particularly its interaction with endothelial protein C receptor (EPCR)] in the pathogenesis of cerebral malaria, one of the most important forms of malaria-induced complications." (PMID 31316507, 2019). "CIDRα1 binds endothelial cell protein C receptor (EPCR), and its expression has been linked to severe malaria in children and adults, whilst rosetting is associated with severe malaria and expression of the DBLα1-CIDRβ/γ/δ head structure." (PMID 29529020, 2018). "The endothelial protein C receptor (EPCR) appears to play an important role in Plasmodium falciparum endothelial cell binding in severe malaria (SM)." (PMID 27255786, 2016). "Although cytoadhesion to Endothelial Protein-C Receptor has a central role in severe malaria, other host receptors are also likely to be involved." (PMID 27835682, 2016). "A recent study showed that Thai malaria patients carrying a mutation in the PROCR gene that leads to higher levels of soluble EPCR in the plasma, were significantly protected against severe malaria compared to other PROCR genotypes." (PMID 26646943, 2015). "These genes include inflammatory responding genes, such as NFκB and CXCL1, parasite protein receptors, such as BSG and PROCR, and the genes involving protection against malaria, such as HLA-B and HAVCR1." (PMID 26099491, 2015). "A dichotomy exists in the PfEMP1 family between variants that encode binding activity for CD36 (CIDRα2–6 domains), a binding property that is associated with mild infections, or endothelial protein C receptor (EPCR) (CIDRα1 domains), a binding property associated with severe malaria." (PMID 34549725, 2021). "In 2013, endothelial protein C receptor (EPCR) was shown to be a new receptor for Plasmodium falciparum erythrocyte protein 1 (PfEMP1) in P. falciparum-induced severe malaria, which may result in a new branch of research on severe malaria." (PMID 31871954, 2019). "Endothelial protein C receptor (EPCR) was recently identified as a key receptor for Plasmodium falciparum erythrocyte membrane protein 1 mediating sequestration of P. falciparum-infected erythrocytes in patients suffering from severe malaria." (PMID 26620701, 2015). "Nevertheless, some contrasting data suggest that genetic diversity in the PROCR gene is not linked with severe malaria outcome in Ghanaian children and that high plasma levels of soluble EPCR are associated with increased mortality in children in Benin." (PMID 26646943, 2015). "Taken together, there is substantial evidence that human genetic variation affecting EPCR functionality could influence severe malaria phenotypes, rendering PROCR a promising candidate for an association study." (PMID 25541704, 2014). "The CIDRα1 domain of PfEMP1 is responsible for binding host endothelial protein C receptor (EPCR), and increasing evidence support that this interaction triggers severe malaria, accounting for the majority of malaria-related deaths." (PMID 32228596, 2020). "One VSA family, P. falciparum erythrocyte membrane protein-1 (PfEMP1), includes a subset of proteins that binds endothelial protein C receptor (EPCR) in human hosts and potentially disrupts the regulation of inflammatory responses, which may lead to the development of severe malaria." (PMID 37791774, 2023).
cerebral malaria (36 papers, 2014 to 2025). A sequestration of Plasmodium falciparum in the brain, which can cause coma and/or seizures. "ICAM-1-binding group A PfEMP1 proteins also bind endothelial protein C receptor and have been associated with cerebral malaria in children." (PMID 31308082, 2019). "As such, the recent discovery that a much smaller gene subset, those containing specific domain types called CIDRα1, and their binding to the endothelial protein C receptor (EPCR) appeared to be associated with cerebral malaria caused great excitement." (PMID 30135713, 2018). "PfEMP1 with CIDRα1 domains that bind to endothelial protein C receptor (EPCR), including those within DC8, have been associated with severe and cerebral malaria." (PMID 39267089, 2024). "Expression of PfEMP1 variants that exhibit binding to chondroitin sulfate in the placenta or to the endothelial protein C receptor (EPCR) has been associated with the development of placental malaria and cerebral malaria, respectively." (PMID 32471507, 2020). "Although the study only shows data for CD36, further studies should address the possibility of a similar effect on receptors implicated in cerebral malaria such as CD54 and endothelial protein C receptor." (PMID 28486940, 2017). "Intercellular adhesion molecule 1 (ICAM-1) and the endothelial protein C receptor (EPCR) are candidate receptors for the deadly complication cerebral malaria." (PMID 27406562, 2016). "Furthermore, host endothelial receptors ICAM1 and endothelial protein C receptor (EPCR) are used for sequestration in the brain and cause cerebral malaria, whereas chondroitin sulfate A binding by some variants (Var2CsA) facilitates placenta binding." (PMID 34414129, 2021). "One argument against an essential role for inflammation is that Endothelial Protein C Receptor (EPCR), currently thought to be a key receptor for cytoadherence in cerebral malaria, is downregulated on microvascular endothelial cells exposed to inflammatory cytokines." (PMID 33648633, 2021). "Recently, parasite strains able to bind both ICAM-1 and Endothelial Protein C Receptor (EPCR) have been isolated and characterized, strengthening the potential role of these two receptors in cerebral malaria." (PMID 35379236, 2022). "PfEMP1 with CIDRα1 domains, known to bind endothelial protein C receptor (EPCR), were consistently found expressed in both children suffering from severe malarial anaemia or cerebral malaria." (PMID 27354391, 2016). "Such P. falciparum cerebral malaria (CM) parasites express a subgroup of group A PfEMP1s that facilitate the dual binding to host intercellular adhesion molecule-1 (ICAM-1) and endothelial protein C receptor EPCR." (PMID 37630491, 2023).
breast carcinoma (33 papers, 2005 to 2025). "For this reason, we also investigated the expression of PROCR, a well-established breast cancer stemness marker linked to higher tumorigenicity." (PMID 29207686, 2017). "PROCR has been implicated as a receptor for protease-cleaved substrates in breast cancer migration and as a marker of colony-forming cells in malignant cell lines." (PMID 25572802, 2015). "PROCR is known to activate several signaling pathways in breast cancer cells, including ERK, PI3K–Akt–mTOR, and RhoA–ROCK–p38 pathways." (PMID 40631077, 2025). "Recently, an association among a polymorphism of the endothelial protein C receptor (EPCR) and factors V and X with hypercoagulability has been reported in breast cancer patients." (PMID 38893201, 2024). "In breast cancer, interfering with PROCR expression significantly decreased the number of CSCs, and dampened tumor growth and recurrence in TNBC." (PMID 36230903, 2022). "We then examined PROCR (a known breast cancer stem cell marker) expression in MDA-MB-231 cells and ESR1 expression in ZR-75-1 cells upon baicalin treatment." (PMID 34295892, 2021). "Here, we show that the endothelial protein C receptor (EPCR), a stem cell marker in hematopoietic, neuronal and epithelial cells, is crucial for breast cancer growth in the orthotopic microenvironment of the mammary gland." (PMID 23593394, 2013). "For example, PROCR+/ESA+ cells showed a higher expression of casein kinase 2 which is involved in the Wnt signaling pathway known to be highly activated in breast cancer stem cells." (PMID 20027313, 2009). "Several new membrane proteins and prognostic markers have been reported to regulate stemness in specific subtypes of breast cancer, such as protein C receptor (PROCR), tetraspanin 8 (TSPAN8), tumor endothelial marker 8 (TEM8), epsilon sarcoglycan (SGCE), and Ki-67." (PMID 36230903, 2022). "Therefore, we want to find out whether ADAM17 also regulate PROCR expression in human breast cancer cells." (PMID 34281556, 2021). "Data analysis using FlowJo v10 confirmed significant upregulation of breast cancer stem cell markers CD56/NCAM1 and CD201/PROCR in C328S-VIM-expressing MCF-7 cells." (PMID 40690373, 2025). "We also investigated the effect of mutant vimentin downregulation on breast cancer stem cell markers CD56/NCAM1 and CD201/PROCR in C328S-VIM-expressing cells upon shRNA treatment." (PMID 40690373, 2025). "The upregulated differentially expressed breast cancer stem cell markers included CD56/NCAM1, POU5F1, PROCR/CD201, ITGA6, and the downregulated were ESR1, PGR, HER2/ERBB2, ABCG2, CD44, CD24, EPCAM, and CDH1." (PMID 40690373, 2025). "Multiple breast cancer stem cell markers such as POU5F1, CD56, CD49f, and CD201/PROCR were also upregulated by C328-VIM, demonstrating increased stemness characteristics in MCF-7 cells as judged by the RNA-Seq analysis." (PMID 40690373, 2025). "Our previous report indicated that PROCR concomitantly activates multiple pathways including ERK, PI3K–Akt–mTOR, and RhoA–Rock–P38 signaling in breast cancer cells." (PMID 35285801, 2022). "Given this knowledge, researches began genetically profiling CD44+ breast cancer tumor cells and identified a CD44+ cell-specific gene, Protein C receptor (PROCR)." (PMID 31379741, 2019). "The expression of key markers associated with proliferation (MKI67, PCNA, CCNB1, MYBL2, BUB1, CCND1), apoptosis (BCL2, CASP7, CASP8, CASP9, CASP3, BAX, APAF1), differentiation (CDH1, CD24, EPCAM, ESR1, NGFR, RUNX1), and breast cancer stemness (CD44, ITGA6, DNER, ALDH1A3, ABCG2, PROCR) was assessed." (PMID 35183258, 2022). "There was also a considerable increase in the expression of others genes described as stem cell markers and expressed in CD44high fractions of normal and breast cancer tissues, including FOXC1(∼11-fold), IGFBP7 (∼8.5-fold), PROCR (∼8.2-fold), LEF1 (∼6.7-fold) and ZEB1 (∼6.6-fold)." (PMID 24498388, 2014).
breast carcinoma (continued). "Thus PROCR and ESA expression defines as yet uncharacterized types of breast cancer stem cells and our data from both cell lines and primary specimens also suggest the existence of still more types of highly tumorigenic cells." (PMID 20027313, 2009).
Sepsis (26 papers, 2005 to 2025). Sepsis is defined as life-threatening organ dysfunction caused by a dysregulated host response to infection. "The endothelial protein C receptor (EPCR, encoded by the PROCR gene) plays a cytoprotective role in sepsis by activating protein C (APC) and mediating APC effects." (PMID 35913450, 2022). "Russell noted that genetic variants in thrombomodulin (TM) and endothelial protein C receptor (EPCR) are associated with mortality in sepsis patients and may predict responses to recombinant human TM or activated protein C (APC) therapy." (PMID 41300910, 2025). "Endothelial protein C receptor (EPCR), a receptor expressed on the endothelium of large blood vessels and correlated to the suppression of proinflammatory cytokine synthesis, may influence the risk of sepsis." (PMID 35682294, 2022). "In septic mice, levels of TM and endothelial protein C receptor (EPCR) decreased by 50% within 12 h of the initiation of sepsis." (PMID 37510681, 2023). "Circulating endothelial MPs carrying endothelial protein C receptor and thrombomodulin have been detected in circulating blood of severe sepsis patients and were further elevated with the progression of sepsis-induced disseminated intravascular coagulation." (PMID 34769139, 2021). "The fixation of PC on the Endothelial Protein C Receptor (EPCR) accelerates the rate of aPC generation and has notably been proven to be critical during sepsis." (PMID 29630665, 2018). "The cytoprotective effects are protease activated receptor 1 (PAR-1) and endothelial protein C receptor (EPCR) dependent and likely underlie protective effects of APC in animal models of sepsis, myocardial infarction and ischemic stroke." (PMID 25032959, 2014). "Specifically, increased TNF in sepsis may be associated with increased EC F3 expression and TF production, as well as down-regulation of THBD and PROCR, resulting in decreased APC generation for suppression of FVIII and FV inactivation." (PMID 32029851, 2020). "A variety of anticoagulant mechanisms, especially the TM, protein C and endothelial protein C receptor (TM‐PC‐EPCR) anti‐coagulation pathway, are suppressed during sepsis or inflammation." (PMID 36629024, 2023). "Since the anticoagulant protease-activated protein C can activate PAR1 when in complex with the endothelial cell protein C receptor (EPCR), which may account for much of the protective effects conferred by activated protein C (APC) in severe sepsis." (PMID 22518344, 2012).